ATM (ATM serine/threonine kinase)
Diseases named in the same sentence as ATM in open-access papers (continued):
Sharing a sentence is not in itself a finding about the gene and the disease.
Obesity (15 papers, 2010 to 2025). Accumulation of substantial excess body fat. "In obesity, surprisingly, mice deficient for the IR specifically in myeloid cells exhibit a protective phenotype associated with decreased ATM accumulation and improved insulin sensitivity." (PMID 31497027, 2019). "Collectively, these results suggest a problem with activation of ATM/ATR-mediated DNA damage response in obesity." (PMID 39092995, 2024). "The miRs expression analysis in ATMs of high fat diet (HFD)-induced obesity in mice compared to lean normal chow diet mice revealed substantial dysregulations of miR-30 which led to a M1 polarization of ATM in the HFD mice." (PMID 34199293, 2021). "Mice, with a deficiency in TGF-β–activated kinase 1 (TAK1), an upstream modulator of NF-κB, in adipocytes, displayed an increased M2 ATM count in WAT, along with an enhanced resistance to HFD or leptin-deficiency-induced obesity." (PMID 32471061, 2020). "These animals exhibited improved insulin sensitivity associated with increased CD206 expression in adipose tissue, independent of differences in ATM content, suggesting p110γ is dispensable for ATM recruitment but promotes M1 responses in obesity." (PMID 31497027, 2019). "However, with obesity, we observed increased accessibility of genes involved in cell cycle regulation (ATM, CDKN1C, BCL2L11), autophagy (HSPA8, IRF8, PEX5), and protein catabolism (CDC34, CTSB, UBB)." (PMID 39872537, 2024). "In patients suffering from obesity, mir-210 is overexpressed in ATM." (PMID 34199293, 2021). "In obesity, prior to ATM infiltration, there is a rise in the number of lymphocytes in the obese adipose tissues, which affects the sustenance of obesity-induced inflammation but is dispensable for the onset of obesity." (PMID 32471061, 2020). "During obesity, adipose tissue accumulates FC and this correlates with increased ATM content." (PMID 31497027, 2019). "Additionally, it was suggested that the proliferation of resident M2 ATMs might also contribute to an increase in the ATM population at the early stages of obesity." (PMID 32471061, 2020). "In the early stages of obesity, ligand–receptor interactions involving LPL, LRP1, and ApoE in ATM contribute to lipid signaling, which regulates inflammation and shapes the metabolic microenvironment of adipose tissue." (PMID 40244284, 2025). "When taken together, we conclude that, upon exposure to the obesity micro-environment, HME1 cells exhibit evident DNA damage accumulation that triggers the activation of the ATM-Chk2-H2A.X pathway." (PMID 38247865, 2024). "However, there was a tendency towards elevated levels of phosphorylated ATM (pATM), ATR (pATR), H2AX (γ-H2AX) and KAP1 (pKAP1) in subjects with obesity." (PMID 39256343, 2024). "The phosphorylation levels of ATM and ATR, as well as those of their recognized downstream effectors, histone H2AX and KAP1, were significantly higher in the VAT biopsies of subjects affected by obesity compared to NW individuals." (PMID 39256343, 2024). "It has previously been demonstrated that progressive obesity decreases BRCA1 abundance in mouse ovaries and in obese mice, there is dysfunction in ovarian ATM phosphorylation in an ovarian follicle stage dependent manner and a subsequent disconnect between ATM and H2AX phosphorylation." (PMID 36702632, 2023). "With one-sided 95% CI, power was sufficient to exclude OR ≥2.0 with obesity for ATM and BRCA2; smoking and alcohol for CHEK2; no breastfeeding for ATM; no oophorectomy for BRCA2 and CHEK2; no tubal ligation for CHEK2; and neighborhood socioeconomic status for all genes." (PMID 40298171, 2025).
cutaneous melanoma (14 papers, 2013 to 2024). A primary melanoma arising from atypical melanocytes in the skin. "Additionally, these results are consistent with our previous finding that signature 3 in TWT cutaneous melanomas is associated with dysregulation of ATM and affects genes that function early during the initiation process of DSB repair." (PMID 38758740, 2024). "The previously unknown loci were annotated to the pigmentation, cardiometabolic, cancer development/progression and immune-regulatory pathways, whilst others are known loci for cutaneous melanoma susceptibility (ATM, and SOX6 for BCC, and GPR98, and DSTYK for both BCC and SCC)." (PMID 36496446, 2022). "The second ATM germline variant carrier (GE15), was a patient affected by cutaneous melanoma." (PMID 38750555, 2024). "However, no DSB repair–associated genomic features identified in cutaneous melanoma whole exomes were significantly associated with signature 3, and the mechanism leading to the downregulation of ATM in the majority of these tumors remains unclear." (PMID 38758740, 2024).
Dystonia (14 papers, 2014 to 2025). An abnormally increased muscular tone that causes fixed abnormal postures. "In this study, we present a Chinese A-T family with two compound heterozygous mutations of ATM presenting with atypically craniocervical dystonia and also present a review of the literatures on the variant A-T cases with dystonia predominance." (PMID 37009283, 2023). "Recently, two independent studies described certain ATM missense mutations in patients that are associated with early-onset dystonia; these patients showed a milder A-T phenotype that was diagnosed at a much later age compared to most typical A-T patients." (PMID 25077176, 2014). "Herein, we provide evidence that c.6200C>A is the disease-causing mutation, carried on a unique ATM haplotype and associated with an unusual phenotype of early-onset dystonia (i.e., A-TWinnipeg)." (PMID 25077176, 2014). "As previously reported, mutations in exon 42 of the ATM gene may predispose to dystonia-dominant A-T, which is needed to be confirmed in further analysis." (PMID 37009283, 2023). "Rare variants in the ATM gene among the 373 dystonia patients detected with smMIPs." (PMID 31920950, 2019). "We successfully established smMIPs in a screening for ATM germline variants in dystonia patients." (PMID 31920950, 2019). "Less severe ATM mutations (eg, leaky splice site or otherwise hypomorphic missense mutations) allow residual ATM kinase activity and give rise to a milder, often later onset, “variant AT” phenotypes, often with predominating dystonia and/or neuropathy phenotypes." (PMID 40464291, 2025). "Thus, we stress the importance of including ATM to the general screening for causes of dystonia." (PMID 31920950, 2019). "Progressive dystonia was associated with ANO3 and a microdeletion in Xp11.4 including the CASK gene, whereas progressive athetosis was seen with ATM and TWNK." (PMID 40326640, 2025). "The study highlights that the proband exhibited dystonia without classical features of A-T, suggesting that ATM mutations can lead to varied clinical presentations, including isolated dystonia." (PMID 39678378, 2024). "A few ATM mutations have been reported in variant A-T cases manifesting isolated generalized or segmental dystonia without any signs of classical A-T." (PMID 37009283, 2023). "Moreover, other dystonia-associated proteins including THAP1, TAF1, ATM, and Gα(olf), contribute to the G1/S checkpoint pathway." (PMID 24936516, 2014). "Notably, a few ATM mutations have been reported in variant A-T cases manifesting as isolated generalized or segmental dystonia without any signs of classical A-T." (PMID 37009283, 2023). "Genetic analyses for dystonia, paroxysmal dyskinesia or episodic ataxia were negative but revealed a compound heterozygote ATM mutation of unknown significance that was first considered responsible for the disorder." (PMID 32647899, 2020). "However, the frequency of ATM mutations in different cohorts of dystonia patients is not well-described." (PMID 31920950, 2019). "Therefore, we tested a cohort of 373 dystonia patients for ATM alterations." (PMID 31920950, 2019). "Thus, ATM haplotyping may provide another testing parameter for dystonia patients." (PMID 25077176, 2014). "Furthermore, the features that were common among previously reported cases but were absent in the PEDIATAX cohort included dystonia with ATM; and spasticity, dystonia, abnormal reflexes, and intellectual disability with SLC2A1." (PMID 40326640, 2025).
metabolic syndrome (14 papers, 2014 to 2025). A cluster of metabolic risk factors for CARDIOVASCULAR DISEASES and TYPE 2 DIABETES MELLITUS. "It seems likely that ATM-dependent stress pathways mediate susceptibility to metabolic syndrome, since chloroquine, which promotes ATM activity and inhibits the JNK stress kinase, increases sensitivity to insulin and decreases vascular disease." (PMID 35453338, 2022). "ATM mutations that cause its inactivation or deficiency have shown a variety of pathological manifestations, including oxidative stress, metabolic syndrome, mitochondrial dysfunction and neurodegeneration." (PMID 32183364, 2020). "While these results offer a greater insight into metabolic syndrome, they raise the possibility that ATM has a greater role in regulating metabolism." (PMID 35453338, 2022). "Similarly, age-associated decreases in ATM protein levels may result in the development of metabolic syndrome, lysosomal accumulation, and protein aggregation that are associated with age-related neuronal diseases and the development of cardiac dysfunction including fibrosis and hypertrophy." (PMID 33868575, 2021). "Apo E knockout mice without ATM protein showed increased IR and were prone to develop a metabolic syndrome." (PMID 32733823, 2020). "Antioxidative treatment that targets the mitochondria in the absence of ATM can decrease the metabolic syndrome, which supports the notion that A-T might be a mitochondrial disease." (PMID 33868575, 2021).
heart failure (13 papers, 2017 to 2026). Inability of the heart to pump blood at an adequate rate to meet tissue metabolic requirements. "Previous studies showed that some genetic alterations, including BRCA1, BRCA2, and ATM mutations, not only predispose to early-onset PCa but also correlate with increased cardiovascular risk and heart failure development." (PMID 40805117, 2025). "Previous investigations have provided evidence indicating that the activation of ROS-induced ataxia-telangiectasia mutated (ATM) protein kinase is evident in conditions of hypertrophy and heart failure." (PMID 37482041, 2023). "For example, as the upstream regulator of DDR, the lncRNA exerts a vital role in resisting heart failure via inhibiting the ataxia telangiectasia mutated (ATM)-DDR signaling pathway and increasing the activation of mitochondrial bioenergetics." (PMID 36895559, 2023). "There was, however, a contradictory result from the same lab demonstrated that depressing senescence by ATM deficiency impaired angiogenesis and accelerated heart failure in response to MI." (PMID 35111365, 2022). "End-stage heart failure induced by pressure overload for 9 weeks was associated with (i) decreased α4 protein expression, (ii) increased activity of ATM/ATR protein kinases and (iii) increased H2AX expression and Ser139 phosphorylation." (PMID 33737606, 2021). "Furthermore, pressure overload-induced heart failure was associated with reduced α4 protein expression, increased ATM/ATR protein kinase activity, increased H2AX expression and Ser139 phosphorylation." (PMID 33737606, 2021). "In addition, genetic and/or pharmacologic reduction of ATM reduced doxorubicin-induced cardiotoxicity and rescued cardiac inflammation and heart failure caused by DNA single-strand breaks." (PMID 32201398, 2020). "As an upstream kinase that senses different stimuli, ATM can be activated by oxidative stress, DNA double‐strand breaks, or even transforming growth factor‐β,36 and these stimuli are associated with MI‐induced heart failure." (PMID 28724653, 2017). "Of note, genetic inactivation of senescence by ATM haplodeficiency inhibited angiogenesis and endothelial tubing formation in response to acute MI, which accelerated heart failure in vivo." (PMID 35111365, 2022). "Our results showed that in response to MI, ATM haplodeficiency accelerated heart failure and increased cardiac fibrosis as well as fibroblast accumulation." (PMID 28724653, 2017). "Additionally, they showed that XRCC1 knockout mice had more severe heart failure, a phenomenon that was later restored by ATM deletion." (PMID 36156462, 2023). "Further investigations for the precise molecular action of ATM against chronic DNA damage may provide a novel therapeutic target for heart failure." (PMID 28436431, 2017). "The present study shows that ATM haplodeficiency decreases fibroblast senescence and vascular endothelial growth factor production and impaired angiogenesis in response to MI, leading to accelerated heart failure." (PMID 28724653, 2017). "In the present study, however, we show that ATM may also play a detrimental role in pressure overload-induced heart failure through NF-κB-dependent induction of inflammatory gene expression." (PMID 28436431, 2017). "Therefore, we investigated the role of ATM in post‐MI cardiac remodeling and heart failure." (PMID 28724653, 2017). "Cardiac echography showed that ATM haplodeficiency did not affect the survival rate but aggravated heart failure at day 28 post MI." (PMID 28724653, 2017).
hereditary cancer syndromes (13 papers, 2017 to 2025). "Despite the relatively small sample size, the study clearly demonstrated a two-hit scenario, a typical mechanism for hereditary cancer syndromes, occurring within ATM mutations in MM." (PMID 41331641, 2025). "We identified two point mutations in KDM6A, which had not previously been identified in medulloblastomas, and validated germline mutations in BRCA2, RAD51D and ATM, which are all involved in DNA repair of double-stranded breaks as well as hereditary cancer syndromes." (PMID 37576901, 2023).
medulloblastoma (13 papers, 2007 to 2026). A malignant, invasive embryonal neoplasm arising from the cerebellum. "Two variants in ATM (p.R189K, p.K2756*) were found in a 16-year-old boy with medulloblastoma inferring an increased risk for developing other cancers." (PMID 28007021, 2016). "There is no clear data on the risk of childhood cancer in individuals carrying a heterozygous ATM pathogenic variant and, to date, the ATM gene has not been described among the subset of genes associated with germline predisposition to medulloblastoma." (PMID 36414972, 2022). "To examine more closely the impact of CHK1 inhibition on DDR proteins we evaluated levels of phosphorylated ATR and ATM and phosphorylated CHK1 in medulloblastoma cells." (PMID 27449089, 2016). "Similarly, ATM, NBN, PALB2, PMS2, PTCH1, and SUFU are tumor suppressor and germline risk genes for medulloblastoma, but CH variants in these genes have not been found in prior studies." (PMID 32508881, 2020). "In human medulloblastoma cells, the DNA damage response was accompanied by activation of both ATR/Chk1, which is activated in response to DNA damage other than double strand breaks, including replication stress, and ATM/Chk2, which is activated predominantly in response to double strand breaks." (PMID 29234490, 2017).
squamous cell carcinoma (13 papers, 2007 to 2025). A carcinoma arising from squamous epithelial cells. "It was shown that upon DNA damage in squamous cell carcinoma cells, ATM kinase is a master switch for the DNp63α phosphorylation at S385 and it’s degradation upon subsequent phosphorylation by CDK2 and p70s6K kinases." (PMID 33375680, 2020). "Cisplatin was previously found to induce the ATM-dependent phosphorylation of ΔNp63α in squamous cell carcinoma (SCC) cells." (PMID 21191146, 2010). "When expression in different histological types was compared, the expressions of ATM, Ku80, IGFBP2, IRS1-pS307, and S6 were significantly higher in neuroendocrinal carcinoma than in adenocarcinoma or squamous cell carcinoma (p<0.05)." (PMID 22348039, 2012).
type 2 diabetes (13 papers, 2012 to 2024). "In the last years, it became evident that ATM gene polymorphisms are associated with higher risk of type 2 diabetes and poorer response to metformin treatment." (PMID 32733823, 2020). "The ATM activity seems to be implicated in the glycemic response to metformin in type 2 diabetes and in CV disease." (PMID 28778179, 2017). "One interesting example is in the 3′ UTR of ATM where six RNA editing sites are linked to a GWAS signal (response to metformin in type 2 diabetes) via their respective edQTL or ASED SNPs." (PMID 28754146, 2017). "Additionally, the gene variant SNP rs11212617 at a locus that includes the ATM was proved to influence the glycemic response to metformin in type 2 diabetes." (PMID 32733823, 2020). "The GWAS SNP rs11212617, which is associated with the effectiveness of metformin in treating type 2 diabetes, lies within a large haplotype block of 340 kb that encompasses genetic variants like rs227091 that can affect RNA editing of the ATM gene based on our edQTL and ASED analysis." (PMID 28754146, 2017). "A-T patients expressing mutated ATM develop insulin resistance and type-2 diabetes." (PMID 24957606, 2014). "In this study, we evaluated the association between rs11212617 polymorphism of ATM gene and rs628031 of SLC22A1 gene with response to treatment in newly diagnosed type 2 diabetes patients." (PMID 27386433, 2016). "Thus, it is possible that RNA editing may play a role in altering the level of the ATM gene product and mediating a poor response to metformin for treating type 2 diabetes, although a definitive proof would require additional functional experiments." (PMID 28754146, 2017).